STT3B (STT3 oligosaccharyltransferase complex catalytic subunit B)
Description:
Catalytic subunit of the oligosaccharyl transferase (OST) complex that catalyzes the initial transfer of a defined glycan (Glc(3)Man(9)GlcNAc(2) in eukaryotes) from the lipid carrier dolichol-pyrophosphate to an asparagine residue within an Asn-X-Ser/Thr consensus motif in nascent polypeptide chains, the first step in protein N-glycosylation. N-glycosylation occurs cotranslationally and the complex associates with the Sec61 complex at the channel-forming translocon complex that mediates protein translocation across the endoplasmic reticulum (ER). All subunits are required for a maximal enzyme activity. This subunit contains the active site and the acceptor peptide and donor lipid-linked oligosaccharide (LLO) binding pockets. STT3B is present in a small subset of OST complexes (OST-B) and mediates both cotranslational and post-translational N-glycosylation of target proteins: STT3B-containing complexes are required for efficient post-translational glycosylation and while they are less competent than STT3A-containing complexes for cotranslational glycosylation, they have the ability to mediate glycosylation of some nascent sites that are not accessible for STT3A. STT3B-containing complexes also act post-translationally and mediate modification of skipped glycosylation sites in unfolded proteins. Plays a role in ER-associated degradation (ERAD) pathway that mediates ubiquitin-dependent degradation of misfolded endoplasmic reticulum proteins by mediating N-glycosylation of unfolded proteins, which are then recognized by the ERAD pathway and targeted for degradation. Mediates glycosylation of the disease variant AMYL-TTR 'Asp-38' of TTR at 'Asn-118', leading to its degradation.
Synonyms: STT3-B; SIMP; FLJ90106; CDG1X
Tractability: Small molecule: a structure with a bound ligand is known. Antibody: UniProt predicts a signal peptide or a membrane-spanning region. PROTAC: ubiquitination databases record sites on it; its protein half-life has been measured.
Target class: Enzyme; Transferase
Gene: Protein-coding gene on chromosome 3 (31,532,521 to 31,638,548, forward strand). Ensembl gene ENSG00000163527.
Subcellular location: Endoplasmic reticulum; Endoplasmic reticulum membrane
Subcellular location (Human Protein Atlas): Endoplasmic reticulum
Pathways (Reactome):
Disease: Maturation of DENV proteins; Maturation of spike protein
Developmental Biology: Regulation of MITF-M-dependent genes involved in extracellular matrix, focal adhesion and epithelial-to-mesenchymal transition
Immune System: PD-L1(CD274) glycosylation and translocation to plasma membrane
Metabolism of proteins: Asparagine N-linked glycosylation
Gene Ontology:
Molecular function: dolichyl-diphosphooligosaccharide-protein glycotransferase activity; protein binding; oligosaccharyl transferase activity
Biological process: ERAD pathway; glycoprotein catabolic process; post-translational protein modification; protein co-translational transfer of dolichol-linked oligosaccharide; protein N-linked glycosylation; protein post-translational transfer of dolichol-linked oligosaccharide; response to unfolded protein; glycoprotein biosynthetic process
Cellular component: endoplasmic reticulum; membrane; oligosaccharyltransferase complex; oligosaccharyltransferase complex B; protein-containing complex; endoplasmic reticulum membrane
Genetic constraint (gnomAD): Loss-of-function variants: 19 observed, 58.12 expected, observed/expected ratio (o/e) 0.33, 90% interval 0.23 to 0.48. The upper end of that interval is the gene's LOEUF score, 0.48, which puts it in group 2 of 6, group 1 being the genes least tolerant of losing a copy. Missense variants: 502 observed, 744.75 expected, observed/expected ratio (o/e) 0.67, 90% interval 0.63 to 0.73. Synonymous variants: 288 observed, 271.53 expected, observed/expected ratio (o/e) 1.06, 90% interval 0.96 to 1.17.
Gene-disease validity (ClinGen):
ClinGen rates the evidence that STT3B causes each of these diseases.
congenital disorder of glycosylation (autosomal recessive): Limited. Congenital disorder of glycosylation (CDG) is a fast growing group of inborn errors of metabolism characterized by defective activity of enzymes that participate in glycosylation (modification of proteins and other macromolecules by adding and processing of oligosaccharide side chains).
Homologues: Orthologues: chimpanzee STT3B (100% identical), macaque STT3B (99% identical), dog STT3B (99% identical), pig STT3B (99% identical), mouse Stt3b (98% identical), rat Stt3b (95% identical), guinea pig STT3B (94% identical), tropical clawed frog stt3b (91% identical), zebrafish stt3b (88% identical), rabbit STT3B (80% identical), Drosophila melanogaster Stt3B (67% identical), Caenorhabditis elegans stt-3 (61% identical). Paralogues in human: STT3A (53% identical), RPL35 (6% identical).
Diseases named in the same sentence as STT3B in open-access papers:
STT3B is named in the same sentence as 15 diseases in open-access papers, as found by Europe PMC text mining. Sharing a sentence is not in itself a finding about the gene and the disease. The quoted sentences say what the papers report.
head and neck squamous cell carcinoma (3 papers, 2024 to 2025). A squamous cell carcinoma that arises from any of the following anatomic sites: lip and oral cavity, nasal cavity, paranasal sinuses, pharynx, larynx, and salivary glands. "Oligosaccharyltransferase subunit (STT3B) was shown to stabilize Epiregulin via N-glycosylation, which is crucial for PD-L1 upregulation and immune escape in head and neck squamous cell carcinoma." (PMID 40519935, 2025).
colon cancer (2 papers, 2025). "The results showed that the expression of human OST complexes OST-A (containing STT3A) and OST-B (containing STT3B), which regulate N-glycosylation, was significantly higher in colon cancer tissues than in normal colon tissues." (PMID 41264633, 2025).
hepatocellular carcinoma (2 papers, 2022). A malignant tumor that arises from hepatocytes. "Then we knocked down endogenous STT3 isoforms in hepatocellular carcinoma cells and found that depletion of STT3A, but not STT3B, significantly suppressed spermine-mediated PD-L1 induction in protein levels." (PMID 36348350, 2022).
viral infection (2 papers, 2022 to 2025). "Our findings enhance the understanding of the role of the N-glycosylation pathway in viral infection and identify STT3B as a potential therapeutic target for controlling PEDV infection." (PMID 39945486, 2025). "Our study showed that STT3B knockdown caused hypo-glycosylation of S protein in the situation of viral infection, while STT3A knockdown did not have such an effect." (PMID 39945486, 2025). "Next, to determine whether STT3 isoforms play a role in glycosylation, we used Vero cells with knockdowns of STT3A or STT3B isoforms and assessed S protein expression in the context of viral infection." (PMID 39945486, 2025).
ZIKV infection (2 papers, 2017 to 2019). "We also found that ZIKV infection was moderately, but significantly, reduced in STT3A and STT3B knockout cells, indicating that the OSTs may also play a role during ZIKV infection." (PMID 28720733, 2017). "Immunofluorescence and electron microscopy analysis have revealed co-localization of HA-tagged MAGT1 and STT3B with DENV replication compartments, which is in line with our experiments showing recruitment of DDOST-GFP at viral replication sites during YFV, WNV and ZIKV infection." (PMID 30650657, 2019).
breast carcinoma (1 paper, 2021). "Our study showed that the expression of several OST subunits including RPN1, RPN2, STT3A STT3B, and DDOST were upregulated in breast cancer samples." (PMID 34778038, 2021).
colorectal cancer (1 paper, 2024). A primary or metastatic malignant neoplasm that affects the colon or rectum. "In light of this, we conducted RNA-seq and RT-qPCR analyses to assess the potential impact of MIIP overexpression or knockdown on the expression of STT3A and STT3B in both human and mouse colorectal cancer (CRC) cell lines." (PMID 38245780, 2024).
congenital disorder of glycosylation (1 paper, 2022). "Defects in STT3A or STT3B genes cause congenital disorders of glycosylation (CDG)." (PMID 36139350, 2022).
hepatic cancers (1 paper, 2020). "For instances, MGAT1, MGAT4A, and GXYLT2 are unfavorable prognostic markers, while MAN1C1, GCNT4, and STT3B are favorable markers in non-hepatic cancers." (PMID 32850363, 2020).
lung carcinoma (1 paper, 2025). "NGI-1, an OST inhibitor targeting both STT3A and STT3B, has been shown to exert antitumor effects in lung cancer by inhibiting the N-glycosylation of EGFR42." (PMID 41413687, 2025).
Obesity (1 paper, 2025). Accumulation of substantial excess body fat. "For example, MACROD2, PHLPP2, CYP2E1, and STT3B are associated with obesity in the body, play a role in fat metabolism, and there is a close link between them and growth traits." (PMID 40244387, 2025). "In addition, several genes were identified that are associated with obesity and play roles in lipid metabolism, including MACROD2, PHLPP2, CYP2E1, and STT3B." (PMID 40244387, 2025).
peripheral nerve injury (1 paper, 2022). Injury to a peripheral nerve. "Consistent with the expression changes of MOGS, the expressions of many metabolism-associated genes, including DDOST, TUSC3, STT3A, STT3B, RPN1, MAGT1, and GANC, were elevated after peripheral nerve injury." (PMID 35575968, 2022).
cancer (4 papers, 2020 to 2025). A tumor composed of atypical neoplastic, often pleomorphic cells that invade other tissues. "STT3B has been reported to participate in stabilization of the immune checkpoint PD‐L1 through the regulation of glycosylation in cancer stem cells." (PMID 39830021, 2025). "Also, the ablation of MGAT5 mRNA in tumor cells leads to less metastatic and less responsive to cytokines phenotype, and STT3B participates in the epithelial-mesenchymal transition (EMT) in cancer cells." (PMID 33425736, 2020). "Glycosylated EREG via STT3B is critical for stabilization of PDL1, suggesting that the enzymes for N-glycosylation is a potential target for cancer therapy." (PMID 38945975, 2024).
tumor (4 papers, 2020 to 2025). "Whether the upregulated expression of STT3B is associated with tumor progression is another important issue that needs to be addressed." (PMID 39830021, 2025). "This mutation causes GUSB protein to be retained in the endoplasmic reticulum, enhancing the stability and transcription of the STT3B subunit, thereby promoting aberrant N-glycosylation of PD-L1, which contributes to tumor immune evasion." (PMID 40963867, 2025). "All 30 DEPs were significantly correlated with DDOST in 179 PAAD tumor tissue samples, among which 22 were strong correlations, including RPN2, SERBP1, CALU, STT3B, YWHAZ and MAPK1." (PMID 39223141, 2024).
STT3B also shares sentences with these, for which no sentence is quoted: infection (2 papers).